DACH2 (dachshund family transcription factor 2)
Description:
Transcription factor that is involved in regulation of organogenesis. Seems to be a regulator for SIX1 and SIX6. Seems to act as a corepressor of SIX6 in regulating proliferation by directly repressing cyclin-dependent kinase inhibitors, including the p27Kip1 promoter. Is recruited with SIX6 to the p27Kip1 promoter in embryonal retina. SIX6 corepression also seems to involve NCOR1, TBL1, HDAC1 and HDAC3. May be involved together with PAX3, SIX1, and EYA2 in regulation of myogenesis. In the developing somite, expression of DACH2 and PAX3 is regulated by the overlying ectoderm, and DACH2 and PAX3 positively regulate each other's expression (By similarity). Probably binds to DNA via its DACHbox-N domain.
Tractability: No criterion of Open Targets' tractability assessment is met for any kind of drug.
Gene: Protein-coding gene on chromosome X (86,148,451 to 86,832,604, forward strand). Ensembl gene ENSG00000126733.
Subcellular location: Nucleus
Subcellular location (Human Protein Atlas): Nucleoplasm
Gene Ontology:
Molecular function: DNA-binding transcription factor activity, RNA polymerase II-specific; RNA polymerase II cis-regulatory region sequence-specific DNA binding
Biological process: regulation of transcription by RNA polymerase II
Cellular component: nucleus; transcription regulator complex
Homologues: Orthologues: chimpanzee DACH2 (99% identical), macaque DACH2 (98% identical), rabbit DACH2 (95% identical), mouse Dach2 (93% identical), rat Dach2 (93% identical), pig DACH2 (92% identical), dog DACH2 (86% identical), tropical clawed frog dach2 (71% identical), zebrafish dacha (69% identical), zebrafish dachb (56% identical), Drosophila melanogaster dac (35% identical), Caenorhabditis elegans dac-1 (24% identical). Paralogues in human: DACH1 (55% identical).
Diseases named in the same sentence as DACH2 in open-access papers:
DACH2 is named in the same sentence as 9 diseases in open-access papers, as found by Europe PMC text mining. Sharing a sentence is not in itself a finding about the gene and the disease. The quoted sentences say what the papers report.
premature ovarian failure (4 papers, 2018 to 2025). "DACH2 is located on chr X, associated with premature ovarian failure, and it has been suggested as a biomarker for ovarian cancer." (PMID 40362382, 2025). "Another study identified an association between several rare mutations in the DACH2 gene and premature ovarian failure, which is characterized by an early loss of germ cells." (PMID 29789566, 2018). "DACH2 (Dachshund Family Transcription Factor 2) may be involved in the regulation of organogenesis and myogenesis and may play a role in premature ovarian failure." (PMID 35615375, 2022). "Additionally deleted in both our families are POF1B, which seems to play a role in the etiology of premature ovarian failure, and DACH2, with an important role in the regulation of brain and limb development and presumed to be implicated in syndromic mental retardation." (PMID 34440285, 2021).
ovarian carcinoma (2 papers, 2012 to 2025). A malignant neoplasm originating from the surface ovarian epithelium. "DACH2 levels were also assessed in a cisplatin sensitive and resistant ovarian cancer cell line, respectively." (PMID 22284433, 2012). "Using the Human Protein Atlas as a tool for cancer biomarker discovery, DACH2 protein was found to be differentially expressed in epithelial ovarian cancer (EOC)." (PMID 22284433, 2012). "DACH2 expression was analysed in the cisplatin sensitive ovarian cancer cell line A2780 and its cisplatin resistant derivative A2780-Cp70." (PMID 22284433, 2012). "The aim of this study was to investigate the prognostic role of DACH2 protein expression in ovarian cancer, by immunohistochemical analysis of 154 EOC samples from two prospective, population-based cohorts." (PMID 22284433, 2012). "Relative risks of death from ovarian cancer and overall death according to DACH2 expression in all patients and patients with serous carcinoma." (PMID 22284433, 2012). "Here, the expression and prognostic significance of DACH2 was further evaluated in ovarian cancer cell lines and human EOC samples." (PMID 22284433, 2012). "While the role of DACH2 in human tumourigenesis remains unexplored, alterations of DACH1 expression has been described in several cancer forms, e.g. breast, prostate, endometrial, gastric and ovarian cancer." (PMID 22284433, 2012).
serous carcinomas (1 paper, 2012). "Associations between DACH2 expression and clinicopathological parameters in all patients and patients with serous carcinoma." (PMID 22284433, 2012). "In multivariable analysis, DACH2 remained an independent prognostic factor in patients with serous carcinoma for both OCSS (HR = 2.01, 95% CI 1.05-3.85, p = 0.035) and OS (HR = 2.13, 95% CI 1.12-4.08, p = 0.022), but not in the full cohort." (PMID 22284433, 2012). "DACH2 expression was significantly higher in carcinoma of the serous subtype compared to non-serous carcinoma." (PMID 22284433, 2012). "Moreover, DACH2 expression was found to be significantly higher in EOC of the serous subtype compared to non-serous carcinoma, and an independent predictor of poor survival in the former." (PMID 22284433, 2012). "This study provides a first demonstration of DACH2 protein being expressed in human fallopian tubes and EOC, with the highest expression in serous carcinoma where DACH2 was found to be an independent biomarker of poor prognosis." (PMID 22284433, 2012). "The distribution of DACH2 in tubal epithelium was similar in serous and non-serous carcinomas (data not shown)." (PMID 22284433, 2012).
cancer (3 papers, 2012 to 2021). A tumor composed of atypical neoplastic, often pleomorphic cells that invade other tissues. "DACH2 is an independent prognostic biomarker that can be used at the initial diagnosis of cancer (UCB) to identify patients with a high potential to develop metastasis." (PMID 34150649, 2021). "Apart from providing a first description of the expression and prognostic significance of DACH2 in EOC, this is also, to our knowledge, the first report of DACH2 expression in any human cancer form." (PMID 22284433, 2012). "In the full cohort, high DACH2 expression was significantly associated with poor prognosis in univariable analysis, and in carcinoma of the serous subtype, DACH2 remained an independent factor of poor prognosis." (PMID 22284433, 2012). "Whether DACH2 is prognostic in other cancer forms, and to what extent this might be cancer-type specific, will be of interest to determine in future studies." (PMID 22284433, 2012). "DACH2 staining was significantly higher in carcinomas of the serous subtype compared to nonserous carcinomas (R = 0.244, p = 0.003)." (PMID 22284433, 2012).
tumours (1 paper, 2012). "Kaplan Meier analysis of the entire cohort (n = 143) demonstrated a significantly reduced OCSS (p = 0.046) and OS (p = 0.021) for tumours expressing high levels of DACH2." (PMID 22284433, 2012).
DACH2 also shares sentences with these, for which no sentence is quoted: breast carcinoma (1 paper); clear cell carcinomas (1); dementia (1); ovarian failure (1).